CHI3L1 (chitinase 3 like 1)
Diseases named in the same sentence as CHI3L1 in open-access papers (continued):
Sharing a sentence is not in itself a finding about the gene and the disease.
breast cancer (continued). "Thus, CHI3L1 may support metastatic breast cancer progression, and exploration of this idea has just begun in preclinical models." (PMID 34832904, 2021). "In addition to its effects on breast cancer cells, CHI3L1 impacts immune cells." (PMID 34832904, 2021). "Thus, it might be concluded that mja-miR-35 inhibited breast cancer metastasis by silencing the CHI3L1 gene expression." (PMID 30258444, 2018). "In the present study, the results revealed that shrimp mja-miR-35, which showed antiviral activity in shrimp against white spot syndrome virus (WSSV) infection, could suppress the metastasis of breast cancer by targeting human CHI3L1 gene of M2 macrophages in a cross-phylum manner." (PMID 30258444, 2018). "CHI3L1 binds to IL-13Rα2 on cancer cells and activates MAPK (ERK and JNK) signaling, upregulating c-Fos, c-Jun, and MMP-9, which promotes breast cancer metastasis." (PMID 40643503, 2025). "It is intriguing that CHI3L1 was proposed to promote ovarian cancer malignancy by enhancing tumor stemness, while GPNMB exerted an analogous function in breast cancer." (PMID 40204276, 2025). "Mechanistically, M2 enhances tumor survival via pathways like CCL2/PI3K/Akt/mTOR in breast cancer, IL-6/STAT3 in colon and pancreatic cancers, and CHI3L1 in gastric/breast cancers." (PMID 40940877, 2025). "Moreover, CHI3L1 is amplified in 12–24% of primary tumors in all BC subtypes and in 6–12% of primary tumors in TNBC based on data from The Cancer Genome Atlas/TCGA and Molecular Taxonomy of Breast Cancer International Consortium/METABRIC." (PMID 38605414, 2024). "The effect of CHI3L1 on reducing E-cadherin expression and simultaneously increasing MMP-9 was demonstrated in a study of breast cancer cells by Scully and colleagues." (PMID 39399677, 2024). "Among which, SAA1, SAA2, HP, NAMPT, CHI3L1 and CHI3L2 have been reported to act as tumor promoters in multiple cancers including lung cancer, breast cancer and ovarian cancer." (PMID 38763993, 2024). "CAFs isolated directly from breast tumor tissue of transgenic mice and cocultured with breast cancer cells exhibited a significant upregulation of pro-inflammatory factors: CXCL1, Chitinase-3-like-1 (Chi3L1), and IL-6." (PMID 38562556, 2024). "CHI3L1 enhances type 2 immune responses, stimulates M2 macrophage differentiation and the formation of TGF-β1, and regulates melanoma and breast cancer metastasis through the Sema7a/CHI3L1/IL-13Rα2 axis." (PMID 38003338, 2023). "In a mouse model of breast cancer, co-culturing 4T1 cells with RAW264.7 cells in vitro resulted in a significant increase in CHI3L1, LCN2, and MMP-9 levels in serum, which promoted tumor metastasis." (PMID 38003338, 2023). "Spleen macrophages carrying breast cancer tumors secrete higher levels of proinflammatory mediators CCL2, CXCL2, MMP-9, and CHI3L1 stimulating this increased secretion." (PMID 38003338, 2023). "Chitinase 3-like protein 1 (CHI3L1), secreted by M2 macrophages, promotes the metastasis of breast cancer cells by binding interleukin-13 receptor α2 chain (IL-13Rα2) on the membranes of cancer cells." (PMID 35443644, 2022). "The chitinase 3-like protein 1 (CHI3L1) secreted by M2 macrophages specifically binds to the interleukin (IL)-13 receptor α2 chain (IL-13Rα2) of gastric and breast cancer cells, which contributes to tumor metastasis." (PMID 35246045, 2022). "Both Ksiazkiewicz M and Cohen N found that, in breast cancer, CAF is capable of promoting monocyte chemoattractant protein-1(MCP-1), SDF-1 and chitinase 3-like 1(Chi3L1) secretion." (PMID 36046791, 2022). "Chitinase 3-like 1 (CHI3L1) and lipocalin 2 (LCN2) have been utilized as immune-related biomarkers for disease progression in breast cancer patients and in the 4T1-based immunocompetent intraductal mouse model for TNBC15,16,18." (PMID 33731699, 2021).
breast cancer (continued). "For example, in breast cancer, by secreting monocyte chemotactic protein-1 (MCP-1), SDF-1 and chitinase 3-like 1 (Chi3L1), CAFs are able to facilitate monocyte migration and enhance the tendency of these cells to polarize into the M2 phenotype." (PMID 34635121, 2021). "Alternatively, inhibition of CHI3L1 in mouse models of TNBC supported an active TME and decreased spontaneous and late-stage mammary carcinoma lung metastasis." (PMID 34832904, 2021). "In correlation with the last study, high levels of TAM-derived MMP9 and other factors such as vascular endothelial growth factor (VEGF), chitinase 3 like 1 (CHI3L1) and lipocalin 2 (LCN2), promoted breast cancer metastasis in vivo." (PMID 32326073, 2020). "It was shown that chitinase-3 like protein-1 (CHI3L1), which was upregulated and promoted proinflammatory mediators in breast cancer cells, was inhibited by chitin." (PMID 33339290, 2020). "CHI3L1 and LCN2 have previously been identified as immune-related biomarkers for disease outcome in breast cancer patients as well as for monitoring tumor progression in the intraductal mouse model for TNBC." (PMID 30111338, 2018). "Recombinant CHI3L1 (rCHI3L1) protein was added to gastric cancer cell culture (MKN-45 and AGS), breast cancer cell culture (MDA-MB-231, MDA-MB-435, and MDA-MB-468), or melanoma cell culture (A375) for cell migration assays using Boyden chambers." (PMID 28143526, 2017). "Therefore, CHI3L1 may be an attractive therapeutic target to inhibit breast cancer metastasis." (PMID 24399973, 2013). "In breast cancer, it was found that the migration and polarization of monocytes into M2-TAMs was promoted by CAF-secreted monocyte chemotactic protein-1 (MCP-1), IL-6, CXCL12, and chitinase 3-like protein 1 (Chi3L1)." (PMID 40805183, 2025). "Expression of the cytokine Chi3l1 (Chitinase-3-like 1) was reduced in tumors lacking the transcription factor Stat3, which is commonly overactive in breast cancer and promotes an immunosuppressive tumor microenvironment." (PMID 40391215, 2025). "This article does not summarize all diseases that CHI3L1 participates in but lists in-depth studies on several diseases, including atherosclerosis, breast cancer, endometrial cancer, colorectal cancer, Alzheimer’s disease, and liver disease." (PMID 38003338, 2023). "CHI3L1 has been detected in the sera of patients with breast carcinomas but not in healthy individuals." (PMID 35309358, 2022). "The remainder of this review will focus on the factors identified by EMT manipulation (CD73, HO-1, TDO2, GM-CSF, M-CSF, CHI3L1 and OPN) and will highlight preclinical and clinical studies that demonstrate how each impact breast cancer metastasis and immune suppression." (PMID 34832904, 2021). "In addition to altering tumor cell metabolism and cytokine secretion, our group and the Weinberg group identified other secreted factors, such as CHI3L1 and OPN, that are modulated by EMT in breast cancer models." (PMID 34832904, 2021). "Likewise, many were upregulated by recurrent downstream fusions (geneDIB), including SIX2 in thyroid and CHI3L1 and OR1D4 in breast cancers." (PMID 32631391, 2020). "CHI3L1 and LCN2, two immune-related biomarkers used for monitoring intraductal tumor progression and breast cancer patient prognosis, confirmed the differential tumor progression and immunology with differential levels in spleens, primary tumors and serum of both models." (PMID 31921184, 2019). "Using the breast mark database, we were however not able to link high or low expression of CHI3L1 in distinct subtype of breast cancer to increased or reduced survival." (PMID 31482369, 2019). "Second, six genes, CHI3L1, CXCL8, FOXC2, SERPINE1, SFRP2, and TF, which are grouped within the highest enrichment GO term, “positive regulation of angiogenesis”, have been reported to play roles in various cancer processes, including breast cancer." (PMID 30205506, 2018).
breast cancer (continued). "Chitinase 3-like 1 (Chi3l1), also known as breast regression protein 39 (BRP-39), has been more emphasized in cancer and lung inflammation due to human homolog YKL-40, which is mainly expressed in breast cancer cells and lung macrophages." (PMID 29403003, 2018). "Adding CHI3L1 protein to gastric cancer cell (MKN-45 and AGS) and breast cancer cell (MDA-MB-231, MDA-MB-435, and MDA-MB-468) cultures promoted the phosphorylation of ERK and JNK but not Src and AKT, which was abolished by IL-13Rα2 gene silencing in cancer cells." (PMID 28143526, 2017). "When the antibody directed against CHI3L1 (anti-CH3L1) was present in co-cultures of isolated M2 cells and gastric or breast cancer cells, the number of invaded cancer cells was significantly decreased compared with that of untreated co-cultures of isolated M2 cells and cancer cells." (PMID 28143526, 2017). "Western blots showed that CHI3L1 protein was present in the sera of gastric and breast cancer patients but not in the sera of healthy donors." (PMID 28143526, 2017). "In summary, these data showed that the M2-secreted chitinase 3-like protein 1 (CHI3L1) could promote the metastasis of gastric and breast cancer cells by triggering the mitogen-activated protein kinase (MAPK) signaling pathway." (PMID 28143526, 2017). "Localization of CHI3L1 in lung tissue samples by immunofluorescence showed that CHI3L1 was expressed by lung epithelial cells (CC10+ cells), and that this expression was increased in the airways of mammary tumor bearing mice compared to controls." (PMID 24399973, 2013). "We also demonstrate that in vivo treatment with chitin microparticles, a substrate for CHI3L1, resulted in decreased production of CHI3L1, CCL2, CXCL2, and MMP-9 in BALF, and more specifically by interstitial and alveolar macrophages of mammary tumor-bearing mice." (PMID 24399973, 2013). "CHI3L1(YKL40) may serve as a new target for anti-angiogenic therapy that can be combined with neoadjuvant chemotherapy to reduce chemoresistance and inhibit metastasis in breast cancer patients." (PMID 38543093, 2024). "For verification of the mammary tumor disease progression either with or without additional macrophages, two immune-related proteins CHI3L1 and LCN2, which both have been identified as prognostic biomarkers in breast cancer patients, were incorporated in the current study." (PMID 30111338, 2018). "Furthermore, local and systemic levels of CHI3L1 and LCN2, two immune-related biomarkers used for prognosticating and monitoring disease in breast cancer patients and mice, provided an additional verification of the tumor progression in 4T1 inoculated mice with and without RAW264.7 macrophages." (PMID 30111338, 2018). "However, the role of CHI3L1 in inducing angiogenesis by macrophages at the pulmonary microenvironment to support newly arriving breast cancer cells is not yet known." (PMID 24399973, 2013). "Chitin microparticle suppression of CHI3L1 could counteract this, and our prior findings of increased IFN-γ levels in chitin microparticle-treated tumor-bearers is consistent with this hypothesis, as these mice show decreased mammary tumor growth." (PMID 24399973, 2013). "In our previous study, it was revealed that the CHI3L1 protein was specifically secreted by M2 macrophages and was not expressed in MDA-MB-231 breast cancer cells." (PMID 30258444, 2018). "We have previously shown that splenic macrophages from mammary tumor-bearing mice secrete higher levels of the pro-angiogenic molecules CCL2, CXCL2, and MMP-9 (compared to non-tumor bearers) and that CHI3L1 stimulates this increased production." (PMID 24399973, 2013).
glioma (111 papers, 2008 to 2025). A benign or malignant brain and spinal cord tumor that arises from glial cells (astrocytes, oligodendrocytes, ependymal cells). "The CHI3L1-encoded protein drives tumor growth, migration, and invasion in gliomas, with its expression levels correlating with tumor malignancy and adverse prognosis." (PMID 40535771, 2025). "Recent studies have shown that CHI3L1 expression is upregulated across all stages of glioma and is closely linked to tumor survival, growth, and invasion." (PMID 39827337, 2025). "Multivariate Cox regression analysis indicated that POSTN and CHI3L1 were positively associated with poor prognosis of gliomas." (PMID 39574472, 2024). "To further understand the influence of mutations in the EMP3 and CHI3L1 genes on the prognosis of glioma patients, we performed a predictive analysis and a t-test, respectively." (PMID 37887529, 2023). "In MES glioma with the highest expression of CHI3L1, CHI3L1 expression was also associated with the level of CD274 (PD-L1)." (PMID 36276655, 2022). "Expression of a three-gene signature, comprised of TGFBI, IGFBP3, and CHI3L1, has previously been associated with glioma tumor cell invasion and migration and poor patient survival." (PMID 34539622, 2021). "In support of this, PDGFD and PDGFRB were positively correlated with a three-gene signature (TGFBI, IGFBP3, and CHI3L1) associated with glioma tumor cell invasion and migration and poor patient survival." (PMID 34539622, 2021). "This study is the first suggestion, to our knowledge, of a direct link between NF1 loss in glioma and production of CHI3L1 by neoplastic cells." (PMID 29643433, 2018). "CHI3L1 is expressed in a subset of gliomas, and an in vitro study has implicated CHI3L1 in promoting glioma cell invasion and survival." (PMID 29643433, 2018). "The link between CHI3L1 expression and glioma pathological grade indicated us to check the association between patient survival and Chitinase 3-Like 1 expression." (PMID 27121858, 2016). "Our data showed that mRNA expression level of CHI3L1 in glioma specimen was associated with tumour malignancy and patient overall survival." (PMID 27121858, 2016). "CHI3L1 expression is associated with the mesenchymal subtype of gliomas which has a poorer survival." (PMID 23805239, 2013). "CHI3L1 encodes for YKL-40, which is a secreted protein that has been reported to be overexpressed in a number of different cancers, including glioma, and has been proposed as a new therapeutic target." (PMID 18781180, 2008). "Notably, CHI3L1/YKL-40 demonstrates potential as a prognostic biomarker for grade 4 glioma, showing an inverse association with overall survival." (PMID 39063215, 2024). "CHI3L1 is strongly associated with immunosuppression in glioma-associated macrophages." (PMID 39619148, 2024). "Similarly, in gliomas, CHI3L1 expression is associated with glioma prognosis, and the prognosis of glioma patients with high CHI3L1 expression is poor." (PMID 37887529, 2023). "We also explored the association between IL-6 and YKL-40 with WHO tumor grade in gliomas WHO grade II-IV, the association between CHI3L1 rs4950928 SNP genotype and plasma YKL-40 levels and differences in plasma IL-6 and YKL-40 levels between patients with newly diagnosed and recurrent GBM." (PMID 32363159, 2020). "Therefore, CHI3L1 associated with NTRK2 seemed to be able to provide new information on glioma prognosis." (PMID 30991699, 2019). "This suggested that CHI3L1 is positively associated with glioma progression." (PMID 27121858, 2016). "At first we checked whether the CHI3L1 mRNA level is associated with the different histopathological grade of glioma." (PMID 27121858, 2016). "The role of CHI3L1 as an oncogenic driver in malignant brain tumors extends beyond gliomas, indicating its importance in tumor aggressiveness, including growth dynamics, migratory tendencies, treatment resistance, and patient survival rates." (PMID 39827337, 2025).
glioma (continued). "Its predictive power for survival aligns with the roles of these genes in glioma biology: CHI3L1 promotes invasiveness via NF-κB activation, while IGFBP2 enhances angiogenesis through IGF signaling." (PMID 40535771, 2025). "Further research is needed to fully understand the functional role and clinical implications of CHI3L1 in glioma progression and treatment response." (PMID 39033204, 2024). "As regard to molecular mechanisms, CHI3L1 mRNA was found to be abundant in glioma cells and reactive astrocytes, while low in neurons and macrophages through in situ hybridization approaches." (PMID 39033204, 2024). "Despite evidence that CHI3L1 has been found to be abnormally expressed in solid tumors and neural disorders and is closely related to patient survival, the role of CHI3L1 in gliomas and the potential mechanism remain undefined." (PMID 39000203, 2024). "In our study, we explored the predictive value of CHI3L1 in gliomas and constructed a prediction model based on CHI3L1, which is aberrantly expressed in a variety of solid tumors and neurodegenerative lesions." (PMID 39000203, 2024). "Subsequent in vivo and cellular experiments confirmed the expression levels of CHI3L1 in gliomas and their correlation with ORGI." (PMID 39000203, 2024). "Brain tumors such as glioma highly express CHI3L1 by interacting with CD44 on the surface of glioma stem cells (GSCs) that result in activating the Akt and β-catenin signaling cascades." (PMID 38667293, 2024). "Gliomas from the CGGA cohort were stratified into CHI3L1 high and low expression groups based on the median mRNA expression levels of CHI3L1 in gliomas." (PMID 39000203, 2024). "In gliomas, CHI3L1 reprograms the tumor microenvironment (TME) by promoting NF-κB pathway activation, regulating tumor malignancy and local invasiveness, making it a potential therapeutic target for gliomas." (PMID 39445005, 2024). "Our work identified the prognostic value of CHI3L1 in gliomas, suggesting it is an adverse factor for patients." (PMID 39000203, 2024). "We then examined the transcriptional levels of CHI3L1 in gliomas using data from the Chinese Glioma Genome Atlas (CGGA) and The Cancer Genome Atlas (TCGA) cohorts, revealing significantly higher expression levels of CHI3L1 in glioma samples." (PMID 39000203, 2024). "CHI3L1, also known as YKL-40, is linked to GBM mesenchymal subtypes and serves as a marker for high-grade glioma." (PMID 39619148, 2024). "K-M curves were drawn to evaluate the impact of CHI3L1 on patients’ OS, and the patients with lower expression levels of CHI3L1 in gliomas experienced a significantly longer OS than patients with higher expression levels." (PMID 39000203, 2024). "In summary, this study investigated the relationship between CHI3L1 and glioma progression and constructed a prediction model based on CHI3L1 and oxidative stress." (PMID 39000203, 2024). "To validate the function of CHI3L1 in glioma progression, we silenced CHI3L1 in the U87MG cell line (U87MG_sh1)." (PMID 39000203, 2024). "Meanwhile, the knockdown of CHI3L1 inhibited glioma growth in vitro, and real-time Quantitative PCR (qPCR) confirmed decreased ORG expression upon CHI3L1 knockdown, suggesting the potential prognostic value of CHI3L1 as a therapeutic target for glioma." (PMID 39000203, 2024). "We provided a deeper insight into the expression of CHI3L1 in the glioma malignant cells by integrating scRNA-seq data into the analysis, which displayed differential expression pattern of CHI3L1 in glioma." (PMID 39033204, 2024). "In our study, we elucidated the prognostic predictive value of CHI3L1 in gliomas and identified the relationship between CHI3L1 and increased levels of local oxidative stress in gliomas through DEG and pathway enrichment analysis." (PMID 39000203, 2024). "we found that SAMD8, RER1, MXI1, and CHI3L1 were highly expressed in most of the glioma tumor microenvironment cells." (PMID 37934565, 2023).